ADAM8 (ADAM metallopeptidase domain 8)
Description:
Possible involvement in extravasation of leukocytes.
Synonyms: CD156a; MS2; CD156
Tractability: Small molecule: a structure with a bound ligand is known; a high-quality ligand is known; it belongs to a druggable protein family. Antibody: its Gene Ontology location is reachable by antibodies, with high confidence; UniProt predicts a signal peptide or a membrane-spanning region. PROTAC: its protein half-life has been measured; a small molecule that binds it is known.
Target class: Metallo protease MAM clan; Metallo protease; Protease; Enzyme; Metallo protease M12B subfamily
Gene: Protein-coding gene on chromosome 10 (133,262,416 to 133,276,909, reverse strand). Ensembl gene ENSG00000151651.
Subcellular location: Membrane
Pathways (Reactome):
Extracellular matrix organization: Degradation of the extracellular matrix
Immune System: Neutrophil degranulation
Gene Ontology:
Molecular function: immunoglobulin receptor binding; metallopeptidase activity; protein binding; tumor necrosis factor receptor superfamily binding; calcium ion binding; cell adhesion molecule binding; metalloendopeptidase activity; serine-type endopeptidase activity; zinc ion binding
Biological process: cellular response to hypoxia; inflammatory response; positive regulation of membrane protein ectodomain proteolysis; positive regulation of neutrophil extravasation; regulation of cell-cell adhesion; signal release; angiogenesis; canonical NF-kappaB signal transduction; cell morphogenesis; extracellular matrix disassembly; leukocyte migration involved in inflammatory response; lymphocyte chemotaxis; negative regulation of neuron apoptotic process; positive regulation of acute inflammatory response; positive regulation of bone resorption; positive regulation of cell adhesion; positive regulation of cellular extravasation; positive regulation of eosinophil migration; positive regulation of epithelial to mesenchymal transition; positive regulation of fibronectin-dependent thymocyte migration; positive regulation of innate immune response; positive regulation of MAPK cascade; positive regulation of phosphatidylinositol 3-kinase/protein kinase B signal transduction; positive regulation of protein processing; positive regulation of protein secretion; and 4 more
Cellular component: cell surface; cytoplasm; dense core granule membrane; phagolysosome; plasma membrane; podosome; specific granule; tertiary granule; alpha9-beta1 integrin-ADAM8 complex; ficolin-1-rich granule membrane; specific granule membrane; tertiary granule membrane; membrane
Genetic constraint (gnomAD): Loss-of-function variants: 100 observed, 82.98 expected, observed/expected ratio (o/e) 1.21, 90% interval 1.02 to 1.42. The synonymous counts are far from expectation, so gnomAD's model fits this gene poorly and the ratio says little. Missense variants: 1,091 observed, 971.43 expected, observed/expected ratio (o/e) 1.12, 90% interval 1.07 to 1.18. Synonymous variants: 490 observed, 410.06 expected, observed/expected ratio (o/e) 1.2, 90% interval 1.11 to 1.29.
Homologues: Orthologues: chimpanzee ADAM8 (98% identical), macaque ADAM8 (90% identical), pig ADAM8 (66% identical), rabbit ADAM8 (65% identical), rat Adam8 (63% identical), dog ADAM8 (63% identical), mouse Adam8 (63% identical), guinea pig ADAM8 (62% identical), zebrafish adam8a (38% identical), zebrafish adam8b (37% identical). Paralogues in human: ADAM19 (34% identical), ADAM12 (33% identical), ADAM28 (33% identical), ADAM33 (33% identical), ADAM15 (32% identical), ADAM9 (29% identical), ADAM7 (27% identical), ADAM11 (25% identical), ADAM22 (25% identical), ADAM20 (24% identical), ADAM23 (24% identical), ADAM29 (24% identical), and 8 more.
Diseases named in the same sentence as ADAM8 in open-access papers:
ADAM8 is named in the same sentence as 105 diseases in open-access papers, as found by Europe PMC text mining. Sharing a sentence is not in itself a finding about the gene and the disease. The quoted sentences say what the papers report.
breast carcinoma (26 papers, 2014 to 2025). "In the context of breast cancer, ADAM8 was found to be widely expressed and associated with a poor prognosis." (PMID 40427200, 2025). "ADAM8 has been implicated in the increase of cellular motility in pancreatic cancer, in breast cancer, in primary brain cancer and prostate cancer." (PMID 36910158, 2023). "Our studies show ADAM8 is widely expressed in breast cancer and provide support for both a diagnostic and prognostic value of the ADP2 IHC assay developed here." (PMID 37568162, 2023). "Our studies show ADAM8 is widely expressed in breast cancer and provide support for both a diagnostic and prognostic value of the ADP2 IHC assay." (PMID 37568162, 2023). "Up‐regulation of ADAM8 in breast cancer has been linked to increased cell invasion and metastasis via β1 integrin mediated mechanisms." (PMID 33314720, 2021). "Together, these findings demonstrate that ADAM8 is aberrantly expressed in a large number of breast cancers, in particular in TNBCs, and its expression is associated with a worse prognosis." (PMID 24375628, 2014). "Our data demonstrate evaluation of tumors for the presence of ADAM8 may also be useful to stratify breast cancer patients into high-risk vs low-risk prognostic groups." (PMID 37568162, 2023). "ADAM17 may not only function in its cell-associated form but might be also released as soluble ectodomain by the action of ADAM8 resulting in a cell-associated remnant form as was recently shown in breast cancer cells." (PMID 35892600, 2022). "One such proteolytically active family member is the metalloproteinase-disintegrin 8 (ADAM8), strongly associated with tumor aggressiveness, progression, and reduced survival in various cancers including breast cancer, pancreatic ductal adenocarcinoma (PDAC), and GBM." (PMID 35371977, 2022). "Notably, other miRNAs found modulated by ADAM8 in this study have been recently reported to help predict breast cancer risk and tumor relapse in TNBC patients." (PMID 27039296, 2016). "These included urokinase plasminogen activator (PLAU) a well characterized prognostic and predictive marker for breast cancer invasion, the cell adhesion metallopeptidase ADAM8, implicated in tumor-progressive degradation of ECM proteins, and a pro-inflammatory cytokine, TNFSF12." (PMID 24498382, 2014). "While all of the ADAM8-regulated miRNAs have been implicated in various aspects of tumorigenesis, we were particularly interested in miR-720 since it has been reported to be highly expressed and abundantly released from breast cancer cells and detected in the blood of patients with multiple myeloma." (PMID 27039296, 2016). "Immunohistochemistry (IHC) and a breast cancer cell line microarray revealed that ADAM8 was present in approximately one-third of breast cancers, with high levels linked to adverse outcomes in hormone receptor-positive/HER2-negative subtypes." (PMID 40427200, 2025). "Adam8 has been considered an important participant in invasive malignant tumors, including breast cancer, pancreatic cancer, and brain cancer, and Tuba1b, as a key regulator of osteosarcoma and is related to the lifetime of colon adenocarcinoma." (PMID 40303139, 2024). "In Triple-negative breast cancer, ADAM8 was able to induce miR-720 by activating a β1-integrin to the ERK signaling pathway." (PMID 39329961, 2024). "Ongoing studies seek to discover additional human breast cancer patient-derived xenograft or cell line models with uniform ADAM8 expression to demonstrate the full ADP therapeutic potential." (PMID 38675197, 2024). "Overall, 33.9% (166/490) of the breast cancer population was ADAM8-positive, including Hormone Receptor (HR) and Human Epidermal Growth Factor Receptor-2 (HER2) positive cancers, which were tested for the first time." (PMID 37568162, 2023). "ADAM8 is another proteolytic enzyme which promotes the TEM of breast cancer cells through upregulating MMP9, while ADAM9 facilitates the adhesion of NSCLC cells through upregulating integrin α3β1." (PMID 37190188, 2023).
breast carcinoma (continued). "For instance, in breast cancer cells, it has been revealed that ADAM8 regulates specific miRNAs, such as miR720." (PMID 36910158, 2023). "Human MDA-MB-231 breast carcinoma cells with ADAM8 knocked down, referred to as ADAM8-KD cells, and scrambled control (ADAM8-Ctrl) cells have been employed to explore cell migration in 3D collagen matrices." (PMID 36910158, 2023). "Analysis of ADAM8 expression in breast cancer was extended beyond TNBC to HR−/HER2+ (n = 22), HR+/HER2− (n = 301) and HR+/HER2+ (n = 28) tumors." (PMID 37568162, 2023). "Previously, we showed that high ADAM8 mRNA levels correlate with poor breast cancer patient prognosis." (PMID 37568162, 2023). "Silencing of ADAM8 in human MDA-MB-231 breast cancer cells reduced their migratory potential to invade Matrigel." (PMID 36910158, 2023). "MMP9 and ADAM8 (a disintegrin and metalloprotease) co-regulation has been demonstrated to promote breast cancer BM, with ADAM8 reported to upregulate MMP9 and the shedding of P-selectin glycoprotein ligand (PSGL-1) from breast cancer cells." (PMID 37190188, 2023). "In agreement, CRISPR/Cas9 knockout of ADAM8 in human breast carcinoma cells resulted in the same results, which indicates that the phenomenon of ADAM8 is not limited to a specific cancer type." (PMID 36910158, 2023). "Based on all these findings, it can be assumed that ADAM8 plays a role in cancer cell migration, such as breast cancer cell migration." (PMID 37287457, 2023). "In this study, the function of ADAM8 in breast cancer is refined by providing in vitro cell investigations in 3D collagen fiber matrices of various conditions." (PMID 37287457, 2023). "Freshly cut, consecutive slides of fourteen TMAs, containing 577 primary breast cancer patient samples were selected for IHC analysis of ADAM8." (PMID 37568162, 2023). "In this study, we identified Adam8 as a sox2-dependent protein expressed in MDA-MB-231 breast cancer cells when cocultured with mesenchymal-stem-cell-derived myofibroblast-like cancer-associated fibroblasts (myCAF)." (PMID 37370863, 2023). "To shed light on the role of ADAM8 in cell migration and force generation, we investigated the fiber displacements for both ADAM8-Ctrl and ADAM8-KD human breast cancer MDA-MB-231 cell lines in dense 3.0 g/l collagen matrices." (PMID 37287457, 2023). "Our findings indicate that breast cancer cells preferentially lack ADAM8 to fulfill elevated migratory tasks and provide a mechanophenotype that is characterized by increased fiber displacements suggesting a force-driven migration mode." (PMID 37287457, 2023). "This extensive sample collection allowed us to examine ADAM8 expression for the first time in breast cancer subtypes beyond TNBC (HR−/HER2−), including HR−/HER2+, HR+/HER2− and HR+/HER2+, that we had never examined previously." (PMID 37568162, 2023). "While the ADPs gave good signal with HEK-A8-2D cells, they were unable to recognize endogenous ADAM8 in fixed MDA-MB-231-3D breast cancer cells, despite these cells expressing essentially equal amounts of ADAM8." (PMID 37568162, 2023). "ADAM8 has been shown to be involved in the reduced generation of fiber displacements and in influencing breast cancer cell migration." (PMID 37287457, 2023). "Beyond breast cancer, ADAM8 has also been detected in several other aggressive solid tumors, including lung, liver, pancreas, stomach, colon, bone, and head and neck." (PMID 37568162, 2023). "Overall, our findings support the potential role for the ADP2 IHC assay in both the identification and prognosis of patients with ADAM8-positive breast cancers." (PMID 37568162, 2023). "In this study, we identified Adam8 as a sox2-dependent protein expressed in MDA-MB-231 breast cancer cells when cocultured with MSCs." (PMID 37370863, 2023). "The impact of ADAM8 on breast cancer cell movement in 3D environments and cell mechanics is largely less well understood." (PMID 37287457, 2023).
breast carcinoma (continued). "Previously, we identified the breast cancer cell surface protein ADAM8 as a marker of poor survival, and a driver of Triple-Negative Breast Cancer (TNBC) growth and spread." (PMID 37568162, 2023). "Based on these findings, we conclude that ADAM8 fulfills a crucial function in altering the mechanical phenotype of human breast cancer cells, such as reduced generation of fiber displacements." (PMID 37287457, 2023). "Previously, knockdown and overexpression studies in breast cancer cells demonstrated ADAM8 promotes cell migration, invasion through Matrigel and growth in an anchorage independent fashion, while having little effect on cell proliferation." (PMID 37568162, 2023). "In fact, it has been shown that treatment with an anti‐ADAM8 antibody reduced the primary tumour burden and cancer metastasis in a murine breast cancer model." (PMID 33314720, 2021). "Since we have shown that ADAM8 is required for β1-integrin activation, which is known to participate in adhesion of breast cancer cells to the endothelium, we investigated the potential role of the DI/CRD/ELD domains in miR-720 activation." (PMID 27039296, 2016). "We next sought to confirm that miR-720 is secreted from breast cancer cells and that its secretion is regulated by ADAM8." (PMID 27039296, 2016). "This soluble fraction of ADAM8 was recently found to be shed from malignant breast tumors into the blood of patients." (PMID 27039296, 2016). "Given the importance of ADAM8 in growth and dissemination of TNBC, and its advantageous localization on the tumor cell surface, our studies identify ADAM8 as a promising novel druggable target for the treatment of these breast cancers." (PMID 24375628, 2014). "In the present study, ADAM8 expression levels correlated with a poor prognosis in breast cancer patients and concomitantly with increased numbers of CTCs and metastases in an orthotopic mouse model." (PMID 24375628, 2014). "Serum levels of ADAM8 protein were also significantly higher in patients with breast cancer compared to those with benign disease." (PMID 24375628, 2014). "Here, our analysis of publicly available microarray databases indicated that ADAM8 is overexpressed in aggressive breast cancers, including TNBCs, and correlated with a poor patient outcome." (PMID 24375628, 2014). "Recently, using microarray analysis, we identified ADAM8 as a target of a multistep pathway downstream of NF-κB RelB, which promotes an aggressive phenotype in breast cancer." (PMID 24375628, 2014). "Using the Oncomine microarray database to assess ADAM8 mRNA levels in breast cancer, ADAM8 was identified as one of the more highly expressed genes in human breast tumors in comparison to normal breast tissue." (PMID 24375628, 2014). "In summary, ADAM8 is essential for the growth and spread of MDA-MB-231 cell-derived mammary tumors in an orthotopic xenograft model and consistently, ADAM8 expression is detected in almost half of distant metastases in patients with breast cancer." (PMID 24375628, 2014). "Overall, 33.9% (166/490) of all breast cancers expressed ADAM8." (PMID 37568162, 2023). "Mechanistic evidence for regulation of MMP-9 expression by ADAM8-driven signal transduction in breast cancer cells is presented, lending weight to the idea that metalloproteases can mutually regulate one another in cross-talks collectively referred to as the “protease web”." (PMID 36910158, 2023). "Notably, the correlation of ADAM8 with tumour progression, metastasis, and chemoresistance in various invasive cancers, including pancreatic cancer, breast cancer, and lung cancer, has been previously reported." (PMID 37082201, 2023). "Our current findings significantly expand the potential patient population, suggesting that diagnosis and subsequent therapeutic inhibition of ADAM8-positive tumors may have much broader implications for breast cancer patients than originally anticipated." (PMID 37568162, 2023).
breast carcinoma (continued). "Therefore, we revealed that the motility of ADAM8 knock down MDA-MB-231 human breast cancer cells and ADAM8-Ctrl MDA-MB-231 cells in 3D collagen matrix scaffolds is altered." (PMID 37287457, 2023). "ADAM8-dependent regulation of miRNA-720 was reported earlier in the breast cancer cell line MDA-MB-231 however in the opposite direction, an observation that we could reproduce with a CRISPR/Cas9 generated knockout of ADAM8 in this cell line." (PMID 34368146, 2021). "In breast cancer, ADAM8 promoted tumor dissemination and metastasis." (PMID 32372565, 2020). "Conrad et al28 concluded that ADAM8 could change the adhesive properties of breast cancer MB‐231 cells to endothelia by influencing β1 integrin cell surface localization and activation thereby changing the cell morphology into an invasive phenotype." (PMID 32954649, 2020). "Interestingly, miR-7 is a potent tumor suppressor in breast cancer cells consistent with the observed ability of ADAM8 to repress its expression." (PMID 27039296, 2016). "High ADAM8 expression in breast cancer patients is an independent predictor of poor prognosis." (PMID 27039296, 2016). "Furthermore, ADAM8 was detected by immunohistochemistry in 48 % of all breast cancer-derived metastases." (PMID 27039296, 2016). "Lastly, a recent endpoint study of patient serum samples showed that increased miR-720 levels can be detected in the whole blood of breast cancer patients with metastatic disease, consistent with our data showing high ADAM8 expression in almost half of all metastases in breast cancer patients." (PMID 27039296, 2016). "We confirmed that miR-720 is secreted from TNBC cells, consistent with observations made in other breast cancer lines, and increased miR-720 levels were detected in the blood of mice 7 days following orthotopic implantation of ADAM8-positive TNBC cells, when tumors were barely palpable." (PMID 27039296, 2016). "Interestingly, ADAM8, TOCA1, and CIP4 are all associated with breast cancer metastasis and invadopodia formation." (PMID 25825872, 2015). "Immunohistochemical analysis of 56 human breast cancer-derived metastases revealed that 48.2% (27/56) were positive for ADAM8 expression, including the majority of brain metastases (63%), and significant percentages of lymph nodes (44.5%), liver (29.4%) and other organ metastases (33.3%, 1/3)." (PMID 24375628, 2014). "Thus, the effects of growth under reduced oxygen on ADAM8 expression in breast cancer cells were studied." (PMID 24375628, 2014). "Furthermore, ADAM8 protein levels were found to be higher in the serum of patients with breast cancer versus benign breast disease." (PMID 24375628, 2014). "This led us to investigate ADAM8 expression levels in metastases from breast cancer patients." (PMID 24375628, 2014). "Furthermore, ADAM8 mRNA was an independent predictor of a poor outcome in breast cancer patients." (PMID 38675197, 2024). "The expression of ADAM8 in brain metastases from various primary malignancies has been investigated, and ADAM8 has been found to be elevated in brain metastases derived from primary breast cancer and to aid transmigration across the endothelium and blood-brain barriers." (PMID 36910158, 2023). "Among them are the family of a disintegrin and metalloproteases (ADAMs) that comprise 22 members in humans, whereby ADAM8 has been even shown to cleave fibronectin, which is elevated in certain cancer types, such as breast cancer, but it is still controversially discussed." (PMID 37287457, 2023). "Thus, ~ 30% of all breast cancer patients have ADAM8-positive tumors and could potentially benefit from an ADAM8-targeted therapy." (PMID 37568162, 2023). "Thus, we hypothesize that ADAM8 increases the motility of breast cancer cells into 3D collagen hydrogels and alters the cellular capacity to remodel their ECM environment." (PMID 37287457, 2023).